HOTAIR (HOX transcript antisense RNA)
Diseases named in the same sentence as HOTAIR in open-access papers (continued):
Sharing a sentence is not in itself a finding about the gene and the disease.
breast cancer (continued). "HOTAIR (HOX Transcript Antisense RNA): Found in exosomes from various cancer cells, HOTAIR is an oncogenic non-coding RNA linked to tumor grade and prognosis in several carcinomas, notably breast cancer." (PMID 37760852, 2023). "Elsewhere, it was reported that HOTAIR associates with polycomb repressive complex 2, trimethylate H3K27 to repress the transcription levels of metastasis-related gene suppressors, therefore increase the invasiveness and metastasis of breast cancer." (PMID 37340445, 2023). "Especially, the upregulation of LPR5 could impair the suppressive effect of HOTAIR in breast cancer." (PMID 36816362, 2023). "Thus, shedding light on miR-1246 and HOTAIR's relationship with IL-39 as novel inflammatory mediators for detecting breast cancer growth and metastasis is crucial." (PMID 36865390, 2023). "HOTAIR is overexpressed in patients with major breast cancer subtypes including in TNBC." (PMID 37795578, 2023). "Additionally, The differential expression fold of miR-1246 and HOTAIR revealed a strong positive correlation among breast cancer patients." (PMID 36865390, 2023). "Additionally, serum HOTAIR levels effectively distinguished patients with stage III/IV breast cancer from those with earlier stages, exhibiting 75% sensitivity and 64% specificity (AUC = 0.698 at the cutoff point of 13.69-fold)." (PMID 38114755, 2023). "This study revealed that HOTAIR/miR-1246 exerts an oncogenic impact in patients with breast cancer." (PMID 36865390, 2023). "This study aims to quantify the expression levels of the ESR1, HOTAIR, and miR-130a genes in serum samples obtained from Egyptian female breast cancer patients and examine the correlations between their expression levels and the clinicopathological features of the disease." (PMID 38114755, 2023). "HOTAIR, an oncogenic lncRNA, promotes tumor burden and metastasis, while miR-130a, a tumor suppressor miRNA, exhibits downregulation with advanced stage and metastasis of breast cancer." (PMID 38114755, 2023). "Additionally, a significant positive correlation was observed between ESR1 and HOTAIR expression levels in breast cancer patients." (PMID 38114755, 2023). "An elevation in HOTAIR expression was observed in the serum of breast cancer patients." (PMID 38114755, 2023). "Furthermore, circulation IL-39 in breast cancer patients was found to correlate negatively with their miR-1246 and HOTAIR levels." (PMID 36865390, 2023). "HOTAIR is a chromatin-modifying lncRNA involved in prostate cancer neuroendocrine differentiation, and overexpression of HOTAIR led to increased metastasis of breast cancer cells through manipulating H3K27me." (PMID 36248960, 2022). "The main role of HOTAIR in breast cancer pathogenesis lies in the promotion of metastasis, and many pathways may lie behind this role, including those presented previously: TGFβ, Wnt/β-catenin, PI3K/Akt/MAPK, and vascular endothelial growth factor (VEGF)." (PMID 35328609, 2022). "The connections we established between m6A and HOTAIR-dependent chromatin regulation prompted us to determine how widespread this was and whether it could explain the effects on breast cancer cell phenotype we observed when disrupting m6A783." (PMID 36441764, 2022). "Moreover, this study revealed that HOTAIR interacts directly with the ER protein to increase ER transcriptional activity and as such ligand-independent breast cancer growth." (PMID 36358625, 2022). "Here, we generate a transgenic mouse model with doxycycline-inducible expression of human HOTAIR in the context of the MMTV-PyMT breast cancer-prone background to systematically interrogate the cellular mechanisms by which human HOTAIR lncRNA acts to promote breast cancer progression." (PMID 36579891, 2022). "In sum, we have identified HOTAIR-based NF-κB signaling regulatory circuit that promotes tumorigenic activity in breast CSCs, further indicating that HOTAIR could be a promising target for clinical treatment of breast cancers." (PMID 36273585, 2022).
breast cancer (continued). "In our inducible human HOTAIR murine model, human HOTAIR transcript overexpression was found to promote breast cancer metastasis in vivo, consistent with previous observations in patients and human breast cancer cell lines." (PMID 36579891, 2022). "We hypothesize that HOTAIR dysregulation during breast cancer metastasis leads to an altered chromatin landscape and subsequent changes in gene expression in affected cells by recruiting chromatin remodeling machinery such as the Polycomb complex (PRC2)." (PMID 36579891, 2022). "However, in these samples, the expression of IκBα in breast cancers was significantly decreased, indicating IκBα expression was also negatively correlated with HOTAIR expression also in clinical samples." (PMID 36273585, 2022). "In addition, HOTAIR served as a sponge for miR-601, and a miR-601 inhibitor reversed the effect of HOTAIR silencing on breast cancer progression." (PMID 35328609, 2022). "Furthermore, a previous study demonstrated that HOTAIR was obviously overexpressed in breast cancer samples, and its inhibition repressed the cell growth both in vivo and in vitro." (PMID 36613528, 2022). "We found that HOTAIR overexpression promotes the invasive capacity of breast cancer cells." (PMID 36579891, 2022). "Here, we investigate the function of m6A in HOTAIR-mediated breast cancer phenotypes." (PMID 36441764, 2022). "This makes HOTAIR a candidate prognostic marker in breast cancer." (PMID 35328609, 2022). "Another study disclosed another axis of HOTAIR in breast cancer, HOTAIR/miR‐129‐5p/FZD7 axis." (PMID 35592755, 2022). "In addition, MAPT-AS1, EGOT, SEMA3B-AS1, and HOTAIR were further verified in normal mammary epithelial cells (HBL100) as well as five human breast cancer cell lines by real-time PCR." (PMID 35990656, 2022). "However, trans-regulatory lncRNAs represented by HOTAIR are upregulated in breast cancer and hepatocellular carcinoma." (PMID 35813295, 2022). "We speculate that LncRNA HOTAIR promotes the proliferation and invasion/metastasis of breast cancer (BC) cells by targeting the miR-130a-3p/Suv39H1 axis." (PMID 35619625, 2022). "It has been shown that HOTAIR is capable of altering the state of chromatin in tumor metastasis, and has been found to be upregulated in metastatic breast carcinomas resulting in an altered pattern of PRC2 occupancy from breast epithelial cells to that of embryonic fibroblasts." (PMID 35788171, 2022). "In conclusion, our results revealed that serum PVT1, HOTAIR, NEAT1, PAI-1, and OPN could be promising molecular diagnostic markers for breast cancer." (PMID 33670447, 2021). "HOTAIR expression is overexpressed in various types of breast cancer tissues and cells." (PMID 34367966, 2021). "In conclusion, our data suggest that the serum levels of PVT1, HOTAIR, NEAT1, PAI-1, and OPN could serve as promising diagnostic biomarkers for breast cancer." (PMID 33670447, 2021). "In breast cancer cells and tissues, high HOTAIR expression could promote tumor progression and trigger drug resistance." (PMID 34073224, 2021). "JMJD6 can strengthen HOTAIR transcription by binding to its promoter in breast cancer cells." (PMID 34073224, 2021). "De-regulation of HOTAIR has been mostly described in the evolution of breast cancer (BC)." (PMID 33540611, 2021). "Overall, the involvement of HOTAIR in these signaling pathways contributes to the progression of breast cancer, and HOTAIR might be utilized as a new predictive and prognostic biomarker in breast cancer." (PMID 34527584, 2021). "Moreover, high expression of HOTAIR reportedly contributed to tamoxifen resistance in breast cancer patients." (PMID 33670447, 2021). "HOTAIR overexpression increases the invasive ability of breast cancer cells in vitro and in vivo." (PMID 34869037, 2021).
breast cancer (continued). "Our data also revealed that serum HOTAIR expression could significantly discriminate between breast cancer patients and control subjects with a sensitivity of 62%, a specificity of 64%, and an AUC of 0.65." (PMID 33670447, 2021). "It is necessary to figure out how HOTAIR overexpression is induced in breast cancer." (PMID 34073224, 2021). "Their results showed that siSENSE could knock down specifically and effectively HOTAIR transcript in breast cancer cells." (PMID 34367966, 2021). "Interestingly, HOTAIR induction has been shown to also be important for the invasive growth of Claudin-low breast cancer cells, which are triple-negative cancer subtype with low expression of claudin-3, claudinin-4, and claudinin-7." (PMID 34946977, 2021). "In addition, the serum levels of HOTAIR, MALAT1, PAI-1, and OPN were also reported to have a diagnostic power of 98%, 72%, 80%, and 86% in discriminating breast cancer from fibroadenoma patients." (PMID 33670447, 2021). "For example, the well-characterized lncRNA HOTAIR could promote proliferation and metastasis of breast cancer through either regulating miR-20a-5p/HMGA2 pathway or enhancing the ER expression and ER occupancy on its downstream target genes." (PMID 34244473, 2021). "Also, in breast cancer HOTAIR up-regulates SNAIL expression, as a master regulator of the EMT pathway." (PMID 34123857, 2021). "In the present study, we will focus on HOTAIR’s functions in the progression of breast cancer." (PMID 34073224, 2021). "Besides, HOTAIR-induced CHST15 transcription also helps maintain the stemness of breast cancer cells." (PMID 34073224, 2021). "In addition, HOTAIR sequesters miR-206 to enhance the expression of Bcl-w, an anti-apoptotic protein, thereby promoting the proliferation of breast cancer cells." (PMID 34527584, 2021). "HOTAIR is also regulated by other ncRNAs to regulate breast cancer cell proliferation." (PMID 34073224, 2021). "In addition, the other therapeutic agents against HOTAIR such as tumor specific peptides or Dioscin, have been used to inhibit the expression of HOTAIR in ovarian cancer, breast cancer and gastric cancer." (PMID 34320988, 2021). "This fact along with the regulation of HOTAIR by estrogens via miR-148a could emphasize the importance of HOTAIR upregulation in the induction of angiogenesis and progression of estrogen-dependent cancers such as thyroid and breast cancers." (PMID 35178360, 2021). "HOTAIR can interfere with the main molecular pathways related to breast cancer (BC) development." (PMID 33540611, 2021). "All together, these data indicate that HOTAIR sponges miR-204 in breast cancer cells." (PMID 32466537, 2020). "Investigations demonstrated that HOTAIR is significantly up-regulated in HER2+ breast cancer cells." (PMID 32245498, 2020). "Long non-coding RNA (lncRNA) HOX Transcript Antisense RNA (HOTAIR) has been shown in several studies to participate in the promotion and metastasis of breast cancer, and its single nucleotide polymorphism is a marker for breast cancer." (PMID 33680952, 2020). "HOTAIR, the first gene discovered to have cis- and trans-regulatory effects on gene expression, is overex-pressed in many tumors, such as breast cancer, colorectal cancer and oral cancer, which is closely related to the tumor progression, metastasis and prognosis of patients." (PMID 33346222, 2020). "Similarly, in a trastuzumab-resistant breast cancer cell line SK-BR-3-TR, knockdown of HOTAIR sensitizes BC cells to trastuzumab." (PMID 32397382, 2020). "Several evidences emphasize the crucial role of HOTAIR in breast cancer resistance." (PMID 32245498, 2020). "Moreover, HOTAIR silencing significantly inhibited breast cancer cell metastasis in xenograft mouse models." (PMID 32929060, 2020). "Overexpression of HOTAIR stimulates the invasion and metastasis of breast cancer cells." (PMID 32190687, 2020). "Moreover, HOTAIR has been demonstrated to promote breast cancer progression via transcriptional regulation." (PMID 32486413, 2020).
breast cancer (continued). "It has been shown that hyperactivity of HOTAIR could promote breast cancer malignancy through interaction with PRC2 complex." (PMID 32245498, 2020). "Also, a small-molecule compound AC1Q3QWB was found to act as a selective and efficient disruptor of HOTAIR-mediated recruitment of PRC2 in breast cancer patient-derived xenograft models." (PMID 32929060, 2020). "The lncRNA HOTAIR plays a role in cancer metastasis and its levels are increased in epithelial cancer cells, such as breast cancer, gastric cancer, oral squamous cell carcinoma, glioblastoma multiforme, colorectal cancer, and esophageal squamous cell carcinoma." (PMID 32164712, 2020). "Enforced transcription of HOTAIR could also promote proliferation, invasion and metastasis in gynaecological malignancies and breast cancer, through different mechanisms including up-regulation of BCL-W and sponging miR-206." (PMID 32245498, 2020). "Overexpression of HOTAIR could negatively regulate expression of some tumour suppressor genes, consequently leading to promote breast cancer cell proliferation, invasion and metastasis." (PMID 32245498, 2020). "Subsequently, mechanism research validated the promoting effect of TGF-β1 secreted by CAFs on the transcription of HOTAIR in breast cancer cells, which will enhance the expression of CDK5 (cyclin dependent kinase 5), thereby facilitating the metastasis of breast cancer cells." (PMID 33520725, 2020). "For instance, by reprogramming the chromatin state, the overexpression of the lncRNA HOTAIR was found to promote the invasiveness and metastasis of breast cancer cells, and its expression level in primary tumours was determined to be a potent predictor of final metastasis and death in breast cancer." (PMID 32364285, 2020). "Similarly, it has been observed that there was a correlation between the CC genotype of HOTAIR rs920778 and clinicopathological features such as advanced stage, distant metastasis, and poorly differentiation among a Turkish breast cancer population." (PMID 31956395, 2020). "Thus, HOTAIR controls breast cancer progression via multiple pathways of regulation of gene expression." (PMID 32486413, 2020). "The research suggested that the inhibition of HOTAIR could be a novel target in breast cancer treatment." (PMID 33680952, 2020). "In addition, HOTAIR promotes the invasion of breast cancer cells by affecting the expression of cell surface glycosaminoglycans." (PMID 32164712, 2020). "Silencing of HOTAIR impeded breast cancer cell growth and lung metastasis in vivo." (PMID 33050642, 2020). "In conclusion, our finding showed that HOTAIR inhibition sensitizes breast cancer cells to ionizing radiation, induced severe DNA damage and activated apoptosis pathways, suggesting a possible role of HOTAIR as a novel target for breast cancer radiosensitization." (PMID 30429228, 2019). "In addition to the indicated malignancies, it has also been demonstrated that HOTAIR is up-regulated in various type of breast cancer tissues and cells." (PMID 31796041, 2019). "Interestingly, we found that HOTAIR and EZH2 were highly co-expressed in TERT mutations only subtype of glioma and triple-negative subtype of breast cancer." (PMID 31367244, 2019). "High levels of HOTAIR correlated with metastasis and poor prognosis have been found in lung cancer, hepatocellular carcinoma, breast cancer, gastric cancer, colorectal cancer, cervical cancer, ovarian cancer, head and neck carcinoma, and esophageal squamous cell carcinoma." (PMID 30654440, 2019). "HOTAIR is a well-known lncRNA that was first characterized in breast cancer." (PMID 30988073, 2019). "Other experiments generally support the view that TGF-β1 secreted by cancer-associated fibroblasts (CAFs) activates the TGF-β1/SMAD pathway in breast cancer cells, whereby leading to the positive regulation of HOTAIR transcription and histone modification of the CDK5 signaling pathway." (PMID 31214490, 2019).
breast cancer (continued). "HOTAIR expression is upregulated in breast cancer tissue and its metastasis, and could also predict the eventual metastasis and death according to different expression levels." (PMID 31214490, 2019). "Thus in this study, we investigated the role of HOTAIR–miR-218 axis on radiosensitivity of breast cancer cells." (PMID 30429228, 2019). "The oncogenic role of ANRIL and HOTAIR is reported in the breast cancer model." (PMID 31784542, 2019). "However, significantly reduced clonogenic growth was observed at the concentration of 40μM AQB in glioblastoma and breast cancer cell lines as well as cervical cancer, gastric cancer and melanoma cells which expressed elevated levels of HOTAIR and EZH2." (PMID 31367244, 2019). "Then we compared the level of HOTAIR in different breast cancer cell lines." (PMID 30429228, 2019). "To better understand the shared impact of lncRNAs and miRNAs in the regulatory post‐transcriptional network, we focused here on the relationships between (a) lncRNA H19 and miR‐675, (b) NEAT1 and miR‐204, and (c) HOTAIR and miR‐331 in plasma of early breast cancer (BC) patients." (PMID 30803129, 2019). "Additionally, we demonstrated that HOTAIR and EZH2 are highly co-expressed in TERT Mutation Only subtype of glioma and triple-negative subtype of breast cancer." (PMID 31367244, 2019). "And this may pave the way for the development of new drugs and targeted therapies to treat patients with glioma and breast cancer by blocking HOTAIR/PRC2 interaction." (PMID 30764859, 2019). "Furthermore, correlation analysis in TCGA glioblastoma and breast cancer datasets showed a positive correlation with the expression of HOTAIR and EZH2." (PMID 31367244, 2019). "HOTAIR plays a critical role in oncogenesis, whose expressions significantly increased in a variety of cancers including hepatocellular carcinoma 19, gastric cancer 20, intestinal cancer 21 and breast cancer." (PMID 28941134, 2018). "HOTAIR has been observed to be involved in the regulation of cancer cell proliferation and cancer invasion in breast cancer which could arise from the positive correlation between HOTAIR and Hoxc11 genes." (PMID 29732012, 2018). "Moreover, HOTAIR is reportedly involved in drug resistance and stemness maintenance in breast cancer cell lines." (PMID 29325547, 2018). "While HOXA9 and other HOX genes have been shown to be transcriptionally regulated by HOTAIR in fibroblasts and breast cancer cell lines, it is currently unknown whether a similar regulation of HOXA9 may also occur in glioma." (PMID 29644006, 2018). "Interestingly, HOTAIR is highly expressed in breast cancer compared to normal breast epithelium with recent evidence indicating the increased detection of HOTAIR in peripheral blood mononuclear cells and breast cancer tissues from ER+ and TNBC patients." (PMID 29732012, 2018). "Additionally, this high expression of HOTAIR was also a significant predictor of subsequent metastasis and correlated with a shorter survival time in breast cancer patients." (PMID 29423075, 2018). "Interestingly, they also identified HOTAIR, a long noncoding RNA that stimulates invasion and metastasis in breast cancer, as being differentially methylated and demonstrating a positive expression correlation with methylation." (PMID 30306389, 2018). "Moreover, over 800 genes were newly occupied and repressed by PRC2 following HOTAIR overexpression, including genes known to inhibit breast cancer progression." (PMID 29685978, 2018). "Except from these, HOTAIR was additionally reported to be robustly expressed in the basal-like breast cancer cells and the inhibition of HOTAIR could reduce the basal-like gene expression and growth in vitro studies." (PMID 29423075, 2018). "HOTAIR plays important roles in breast cancer and may be an important target for diagnosis and therapy." (PMID 29515098, 2018).